PDE10A (phosphodiesterase 10A)
Diseases named in the same sentence as PDE10A in open-access papers (continued):
Sharing a sentence is not in itself a finding about the gene and the disease.
Stroke (4 papers, 2017 to 2025). Sudden impairment of blood flow to a part of the brain due to occlusion or rupture of an artery to the brain. "This improvement in motor function with PDE10A inhibition is associated with elevated levels of BDNF in the striatum that has the stroke, and in enhanced angiogenesis and axonal connections in the striatum contralateral to the stroke." (PMID 32378029, 2021). "Different from changes in the other brain regions, however, Pde10a was most consistently increased between 14 and 56 days post-stroke in poorly recovered mice." (PMID 36833381, 2023). "Similar to Pde10a, Adora2a and Drd2 belong to the cAMP signaling pathway, which is known to regulate synaptic plasticity and be involved in functional recovery after stroke." (PMID 36833381, 2023). "In the present study, we took tissue blocks for the BDNF measurement lateral to the stroke, because the goal was to determine if PDE10A inhibition activated BDNF in sensorimotor projections to the striatum." (PMID 32378029, 2021). "Triflusal, a treatment for stroke re-occurrence, targets four genes (PTGS1 (also known as Cox-1), NOS2, NFKB1, and PDE10A) that together have more functional variants in the African population than in any other population (DRPAFR = 37%)." (PMID 29273096, 2017). "Inhibition of PDE10A is site-specific in its role of improving recovery after stroke." (PMID 32378029, 2021). "The application of a PDE10A inhibitor in the subacute phase of stroke, after cell death and secondary injury have taken place, provides an opportunity for selective manipulation of neuronal signaling systems associated with synaptic plasticity particularly strong in the basal ganglia or striatum." (PMID 32378029, 2021). "There are several possible mechanisms of action for PDE10A inhibition in striatal stroke." (PMID 32378029, 2021). "A competitive inhibitor of PDE10A, TAK-063, was administered i.p. beginning 5 days after stroke, a time point at which brain sensitivity to damage-enhancing effects of plasticity drugs is lost." (PMID 32378029, 2021). "The effect of PDE10A inhibition on BDNF induction only in the stroke striatum, and not the contralateral side in the present data, likely is due to the damage from the stroke." (PMID 32378029, 2021). "The PDE10A inhibitor TAK-063 promotes recovery of motor function after striatal stroke but not cortical stroke." (PMID 32378029, 2021). "The use of a PDE10A inhibitor has not been examined in recovery after stroke." (PMID 32378029, 2021). "It is possible that selective induction of BDNF in the striatum may enhance recovery in subcortical or striatal stroke, a common stroke subtype, but not have an effect in other stroke subtypes, such as in cortex or other brain areas in which PDE10A levels are low." (PMID 32378029, 2021).
cardiac hypertrophy (3 papers, 2019 to 2022). "Knock-out and inhibition of PDE10A increases levels of cAMP and cGMP levels in mouse cardiomyocytes and significantly reduces myocardial hypertrophy and myocardial fibrosis caused by chronic neurohormonal stimulation." (PMID 34530505, 2022). "Current research focuses on phosphodiesterase 10A as a new therapeutic target, which expression is elevated in cardiac hypertrophy." (PMID 34064664, 2021). "Whole-body PDE10A KO inhibits Ang-II and pressure overload-induced cardiac hypertrophy, fibrosis and dysfunction, suggesting that pharmacological targeting of PDE10A might represent a potential strategy for the treatment of cardiac fibrosis and heart failure." (PMID 31888098, 2019).
cognitive deficits (3 papers, 2022 to 2026). "Importantly, behavioral and cognitive impairments were partially reversed by either pharmacological inhibition of PDE10A using papaverine or by genetic knockdown of PDE10A." (PMID 41155624, 2025). "PDE1B inhibition enhances D1-receptor signaling, ameliorating negative symptoms and cognitive deficits, while PDE10A inhibition modulates D2-receptor activity, potentially alleviating positive symptoms." (PMID 41835457, 2026).
Dyskinesia (3 papers, 2021 to 2024). A movement disorder which consists of effects including diminished voluntary movements and the presence of involuntary movements. "Since L-DOPA-induced dyskinesia is associated with abnormal corticostriatal transmission, we hypothesized that inhibition of PDE10A would modulate L-DOPA-induced dyskinesia (LID) by regulating corticostriatal activity." (PMID 36015095, 2022). "Celon Pharma has registered a phase 2 clinical trial to examine the efficacy of a PDE10A inhibitor in reducing L-dopa-induced dyskinesia, which is estimated to completein October 2024 (NCT05297201)." (PMID 39056811, 2024).
glioma (3 papers, 2021 to 2025). A benign or malignant brain and spinal cord tumor that arises from glial cells (astrocytes, oligodendrocytes, ependymal cells). "We have previously shown that cAMP inhibits the growth of rat C6 glioma cells, and we know that the PDE10A inhibitor Mardepodect increases the levels of cAMP in the human GBM cell lines used here." (PMID 34359681, 2021). "Moreover, they developed a PDE10A-suppressed GBM model using the RCAS/tv-a system in mice, which caused an aggressive glioma phenotype, promoted a proneural-to-mesenchymal transition, and increased resistance to chemo- and radiotherapy." (PMID 41179677, 2025). "Cell culture analysis also showed that reduced expression of PDE10A activates the PI3K/AKT pathway, contributing to glioma progression and temozolomide resistance." (PMID 41179677, 2025).
heart failure (3 papers, 2019 to 2025). Inability of the heart to pump blood at an adequate rate to meet tissue metabolic requirements. "The study proposes that PDE10A inhibition may represent a promising therapeutic approach for heart failure." (PMID 40070045, 2025). "Inhibition of PDE10A may enhance cardiac structure and function, positioning it as a potential target for the treatment of heart failure and arrhythmias." (PMID 40070045, 2025).
hyperthyroidism (3 papers, 2018 to 2026). Overactivity of the thyroid gland resulting in overproduction of thyroid hormone and increased metabolic rate. "In thyroid tissue, PDE10A displayed significant colocalization between hyperthyroidism-associated GWAS signals and its eQTL signals (PP4 = 0.84)." (PMID 41570039, 2026). "For example, a variant at PDE10A (rs2983514) was associated with both higher risk of hypothyroidism and lower risk of hyperthyroidism." (PMID 30367059, 2018). "Through cross-validation using four methods (SMR, TWAS, mBAT-combo, and PoPS), we identified three core candidate genes (FAM227B, PDE8B, PDE10A) associated with hyperthyroidism, with PDE8B as the sole intersecting gene showing significant association with hypothyroidism." (PMID 41570039, 2026). "Cross-validation by four methods identified FAM227B, PDE8B, and PDE10A as key genes for hyperthyroidism, and PDE8B as the critical gene for hypothyroidism." (PMID 41570039, 2026). "These drugs may regulate hyperthyroidism-related physiological processes by acting on PDE10A and PDE8B, ameliorating disease Phenotypes." (PMID 41570039, 2026). "Through integrated multi-omics analysis, this study is the first to characterize the bidirectional regulatory mechanism of PDE8B in hyperthyroidism and hypothyroidism, alongside the genetic associations of FAM227B and PDE10A with cardiovascular and neurological comorbidities." (PMID 41570039, 2026). "For hyperthyroidism, PDE10A and PDE8B are critical potential targets." (PMID 41570039, 2026). "Through cross-validation of the four methods, 3 intersecting genes for hyperthyroidism (FAM227B, PDE8B, PDE10A) and 1 intersecting gene for hypothyroidism (PDE8B) were finally identified." (PMID 41570039, 2026).
alcohol dependence (2 papers, 2011 to 2014). Physical and psychological dependence on alcohol. "Together these results implicate heightened PDE10A expression in the BLA as a lasting neuroadaptation associated with alcohol dependence." (PMID 24782725, 2014).
Atrophy (2 papers, 2021 to 2025). Any weakening or degeneration, especially through lack of use. "This outcome indicates that the decreased PDE10A and DAT levels detected by PET and SPECT might be caused by both, basal ganglia dysfunction as well as atrophy due to the p.Phe300Leu mutation in the PDE10A gene." (PMID 33917199, 2021).
bladder cancer (2 papers, 2022). "In the Manhattan plot of male bladder cancer cases, there were peaks satisfying a suggestive level of p < 10−5 between LINC00922 and CDH5 in chromosome 16, and between LINC00473 and PDE10A in chromosome 6, but they were outside the genetic regions in the regional plots of GWAS results." (PMID 35328002, 2022).
brain injury (2 papers, 2022 to 2025). Acute and chronic (see also brain INJURIES, CHRONIC) injuries to the brain, including the cerebral hemispheres, CEREBELLUM, and brain STEM. "PDE10A expression has been associated with various injuries, including traumatic brain injury (TBI) and spinal cord injury." (PMID 40429643, 2025). "PDE10A is an important target for the treatment of ganglion dysfunction and neuroinflammation-related diseases, but its possible impact on traumatic brain injury (TBI) is still unclear." (PMID 35463083, 2022).
dementia (2 papers, 2022). Loss of intellectual abilities interfering with an individual's social and occupational functions. "The TBI‐associated dementia‐related increase in PDE expression is unique to PDE11A in that PDE2A, PDE5A, and PDE10A expression remained unchanged." (PMID 36073342, 2022).
developmental delay (2 papers, 2022 to 2025). "SNV in PDE10A cause two distinct phenotypes: a dominant (de novo) childhood-onset form with normal cognition and bilateral striatal MRI T2-hyperintense lesions, and a recessive infantile-onset form with developmental delay and normal imaging." (PMID 40584247, 2025).
glioblastoma (2 papers, 2021 to 2025). The most malignant astrocytic tumor (WHO grade IV). "Loss of the PDE10A gene locus (6q27) could be considered an independent poor prognostic indicator in IDH wild-type glioblastoma, showing lower overall survival." (PMID 41179677, 2025). "The most potent inhibitors of glioblastoma cell viability were the PDE10A inhibitors PF-2545920, PQ-10, papaverine and TC-E 5005, which decreased the percentage of viable cells by 55–95% in at least one of the three cell lines." (PMID 34575827, 2021). "Conversely, in glioblastoma (GBM), PDE10A acts as a tumor suppressor, and its knockdown promotes tumor progression via activation of the PI3K/AKT pathway." (PMID 41179677, 2025). "The PDE10A inhibitors PF-2545920, PQ10 and papaverine, the PDE3/4 inhibitor trequinsin and the putative PDE5 inhibitor MY-5445 potently decreased glioblastoma cell proliferation." (PMID 34575827, 2021). "Further experiments using the PDE10A inhibitor PF-2545920 and the PDE5 inhibitor MY-5445 revealed the synergistic suppression of proliferation in two of the three glioblastoma cell lines tested." (PMID 34575827, 2021). "Our present results allow a cautious conclusion that the potent inhibition of glioblastoma cell viability may be achieved by combining MRP1 inhibitors with PDE inhibitors, especially the PDE10A inhibitor PF-2545920." (PMID 34575827, 2021).
hyperprolactinemia (2 papers, 2015 to 2018). Abnormally high level of prolactin in the blood. "PDE10A inhibitors can avoid hyperprolactinemia as PDE10A expression is low in the pituitary gland." (PMID 25815469, 2015).
Intellectual disability (2 papers, 2020 to 2021). "A recent report demonstrated that in mouse partial loss of miR-137, a locus linked to autism and intellectual disability, impairs postnatal development and regulates synaptic plasticity by targeting the cyclic nucleotide phosphodiesterase family member Pde10a." (PMID 32228681, 2020).
neuroblastoma (2 papers, 2020 to 2022). Neuroblastoma (NB) is the most common solid, extracranial childhood tumor. "As PDE10A is well known to be expressed in neuronal tissues, we used murine brain lysates and the neuroblastoma cell line SH-SY5Y as positive controls in qPCR experiments." (PMID 32587621, 2020). "We used human neuroblastoma cell line SH-SY5Y and murine brain lysates as positive controls for their renowned high levels of PDE10A expression." (PMID 32587621, 2020).
R6 (2 papers, 2021). "In other models of neuronal degeneration, such as the severe R6/2 Huntington mouse, a relatively less-specific PDE10A inhibitor improves memory function." (PMID 32378029, 2021).
Sepsis (2 papers, 2025). Sepsis is defined as life-threatening organ dysfunction caused by a dysregulated host response to infection. "To investigate the role of PDE10A in inflammasome activation in vivo, we employed a clinically relevant acute sepsis model, using LPS followed by ATP as a second signal." (PMID 40429643, 2025). "Given that inflammasome overactivation is central to sepsis pathophysiology, PDE10A represents a promising therapeutic target for diseases driven by inflammation, like sepsis." (PMID 40429643, 2025). "In a clinically relevant acute sepsis model, PDE10A inhibition reduced inflammation and improved sepsis outcomes." (PMID 40429643, 2025). "Inhibition of PDE10A reduced inflammasome-induced cytokine release, attenuated pyroptosis, and improved recovery following nerve injury and sepsis." (PMID 40429643, 2025). "Using both in vitro and in vivo models, we demonstrated that the inhibition of PDE10A reduces inflammasome activation, mitigates inflammation, and improves functional recovery in conditions such as traumatic nerve injury and sepsis." (PMID 40429643, 2025). "Our results show that PDE10A inhibition effectively reduces inflammasome activation, protects against pyroptosis, and improves functional recovery in both sepsis and traumatic nerve injury models." (PMID 40429643, 2025). "This study investigates the effects of PDE10A inhibition on inflammasome-driven inflammation using two PDE10A inhibitors, MP-10 and TP-10, in macrophage and animal models of sepsis and traumatic nerve injury." (PMID 40429643, 2025). "Inhibition of PDE10A with MP-10 and TP-10 reduced cytokine release and cell death, suggesting potential therapeutic benefits for modulating inflammation and improving recovery in conditions like traumatic nerve injury and sepsis." (PMID 40429643, 2025). "Although several PDE10A inhibitors have been tested for safety in humans, mainly for psychiatric disorders, further research is required before advancing to clinical trials for other conditions such as sepsis and trauma." (PMID 40429643, 2025). "Further investigation into PDE10A’s molecular mechanisms in lipid metabolism and ferroptosis may reveal new therapeutic opportunities for immune modulation, particularly for diseases involving dysregulated cell death, such as sepsis or chronic inflammation." (PMID 40502099, 2025). "In this study, we examined the effects of PDE10A inhibition on NLRP3 inflammasome activation and pyroptosis in vitro, using human THP-1 macrophages and mouse-derived macrophages, and in vivo, using sepsis and sciatic nerve injury mouse models." (PMID 40429643, 2025).
Tourette syndrome (2 papers, 2024 to 2025). A neurologic disorder caused by defective metabolism of the neurotransmitters in the brain. "PDE10A inhibitors modulate signaling in the striatal basal ganglia nuclei and are thus of interest as potential therapeutics in treating Tourette syndrome and other movement disorders." (PMID 39056811, 2024).
asthma (1 paper, 2011). "Among the asthma genes identified in genome wide association studies, ROBO1, RORA, HLA-DQB1, IL2RB and PDE10A were differentially expressed during human lung development." (PMID 21699702, 2011). "Among the GWAS asthma genes, ROBO1, RORA, HLA-DQB1, IL2RB and PDE10A were differentially expressed in the human data." (PMID 21699702, 2011). "Among the asthma genes identified in GWAS, ROBO1, RORA, HLA-DQB1, IL2RB and PDE10A showed most significant evidence of involvement in lung development (all adjusted p < 0.001 for differential expression)." (PMID 21699702, 2011). "Among genes identified in asthma GWAS, ROBO1, RORA, HLA-DQB1, IL2RB and PDE10A showed most consistent expression patterns and from asthma candidate genes, e.g. NOD1, EDN1, CCL5 and HLA-G were identified." (PMID 21699702, 2011).
autonomic dysfunction (1 paper, 2018). "Distinguishing clinical features may further include sleep-related phenomena and marked fluctuation in ADCY5 disease, abnormal MRI features in dominant PDE10A disease, and severe exacerbations associated with autonomic dysfunction in patients with GNAO1 mutations." (PMID 29948482, 2018).
chronic obstructive pulmonary disease (1 paper, 2025). A chronic and progressive lung disorder characterized by the loss of elasticity of the bronchial tree and the air sacs, destruction of the air sacs wall, thickening of the bronchial wall, and mucous accumulation in the bronchial tree. "PDE4 inhibitor Roflumilast is FDA-approved for treating severe chronic obstructive pulmonary disease (COPD), but the specific role of PDE10A in NLRP3 inflammasome activation remains unclear." (PMID 40429643, 2025).
Dysarthria (1 paper, 2022). Dysarthric speech is a general description referring to a neurological speech disorder characterized by poor articulation.
gastric cancer (1 paper, 2016). A primary or metastatic malignant neoplasm involving the stomach. "The effects of somatic mutations in genes encoding zinc finger proteins (ZNF721 and ZFYVE16), a purine and pyrimidine metabolism protein (NT5E), carbonic anhydrase(CA1), and cyclic nucleotide phosphodiesterase(PDE10A)on the progress of gastric cancer requires further study." (PMID 27270314, 2016).
Hip dysplasia (1 paper, 2023). The presence of developmental dysplasia of the hip. "Joint hypermobility was present in 64% of all individuals, and hip dysplasia was reported in 6/15 individuals with a PDE10A deletion." (PMID 36935482, 2023).
Hyperglycemia (1 paper, 2016). An increased concentration of glucose in the blood. "We also found improved insulin sensitivity after chronic MP‐10 treatment further supporting the use of PDE10A inhibitors for the management of hyperglycemia." (PMID 27247380, 2016).
Hypomagnesemia (1 paper, 2022). An abnormally decreased magnesium concentration in the blood. "The confirmed drug-target interactions suggest an attenuation of pulmonary vascular remodeling (inhibition of PDE10A), modulation of Hepatitis C (HCV) viral response (inhibition of PKN2), and hypomagnesemia (inhibition of TRPM6)." (PMID 35551258, 2022).
Hypoxic ischemic encephalopathy (1 paper, 2025). "Hypoxic ischemic encephalopathy, but also genetic syndromes that cause specific lesion patterns (e.g. PDE10A mutations) and can be included in DCP cohorts, present a specific neuronal vulnerability that will not be sufficiently reflected in imaging patterns." (PMID 40574970, 2025).
injury (1 paper, 2025). Damage inflicted on the body as the direct or indirect result of an external force, with or without disruption of structural continuity. "By inhibiting PDE10A, MP-10 not only attenuated inflammasome activation but also mitigated some of the downstream effects of nerve injury." (PMID 40429643, 2025). "In our study, the reduced IL-1β cleavage in the sciatic nerve following MP-10 treatment further supported the idea that PDE10A inhibition modulates inflammasome activation in nerve injury, contributing to improved functional recovery and reduced muscle atrophy." (PMID 40429643, 2025). "Additionally, PDE10A inhibition improved motor function recovery following traumatic nerve injury." (PMID 40429643, 2025).